AKT2 (AKT serine/threonine kinase 2)
Diseases named in the same sentence as AKT2 in open-access papers (continued):
Sharing a sentence is not in itself a finding about the gene and the disease.
cancer (continued). "The study highlights a multi-target mechanism, with strong interactions observed against key protein targets in cancer pathways, including HDM2, DNMT1, AKT2, and PARP-1." (PMID 40575462, 2025). "AKT2 was positively correlated with VEGFB and CD274, among others, highlighting its potential involvement in cancer immunology and therapy resistance mechanisms." (PMID 39063239, 2024). "The serine/threonine kinase AKT, also known as protein kinase B (PKB), is a proto-oncogene that has three isoforms, AKT1 (PKBα), AKT2 (PKBβ), and AKT3 (Pub), which have markedly different or even opposing functions in cancer and physiology." (PMID 38375094, 2024). "The dearth of knowledge regarding AKT3 in cancer possibly stems from early reports that it is expressed predominantly in the brain, heart and kidneys, whereas AKT1 and AKT2 are expressed ubiquitously." (PMID 37292818, 2023). "The Cancer Proteome Atlas (TCPA) created a Kaplan Meier (KM) plot for miR-520c-3p targets AKT1, AKT2, AKT3, MTOR, NF-κB (RelA), PDK1, PI3K, and PTEN." (PMID 35634241, 2022). "This warrants a detailed assessment of the role of AKT2 and AKT3 targeting by lncRNAs in regulating cancer cell functions in the future." (PMID 36230902, 2022). "A careful examination of more cell functions influenced by more AKT1-, AKT2-, and AKT3-targeting circRNAs on cancer cells is warranted." (PMID 36230902, 2022). "Although many circRNAs were shown to target AKT1, AKT2, and AKT3, only some were capable of modulating cell functions (apoptosis and migration) in cancer cells based on the literature search." (PMID 36230902, 2022). "Whereas Akt2 promotes growth factors-induced epithelial–mesenchymal transition (EMT), a process that promotes cancer metastasis, Akt1 negatively regulates EMT." (PMID 34419139, 2021). "However, it is unclear how Akt2-induced palladin expression may affect cancer cell migration." (PMID 34419139, 2021). "Capivasertib was previously shown to inhibit all three isoforms of AKT (AKT1, AKT2 and AKT3) in enzyme assays and reduce phosphorylation of its downstream substrates P70S6K or PRAS40 and in vitro growth of a subset of various cancer cell lines and xenografts." (PMID 34066040, 2021). "It has three different subtypes, AKT1, AKT2, and AKT3, which are closely related to the development of human cancer." (PMID 34956562, 2021). "Further investigation showed that phosphorylation of the two Akt isoforms (Akt1 and Akt2) was significantly inhibited by KA39 and KA25 in SW403 and LoVo cancer cells cancer cells." (PMID 33916378, 2021). "AKT, is a serine/threonine protein kinase comprising three isoforms—namely: AKT1, AKT2 and AKT3, whose inhibitors have been recognized as promising therapeutic targets for various human disorders, especially cancer." (PMID 33920446, 2021). "This promotes phosphorylation of WASP-interacting protein (WIP) by AKT2 which in turn stabilizes YAP/TAZ, and supports cancer stem cell survival and phenotypic maintenance." (PMID 33505918, 2020). "From these findings, we can develop an understanding of the molecular mechanisms, like the AKT2 or MAPK pathways, of chemo- and radiation-resistant cancer cells with stem cell-like phenotypes." (PMID 31608140, 2019). "EP decreased migratory and invasive effects of cancer cells while inhibiting the expression of total AKT1, AKT2, BCL-XL, Cyclin D1 and c-Myc in the tested IBC cells." (PMID 30837881, 2019).
cancer (continued). "In this cascade, both PI3K and mTORC2 are required as upstream regulators for the hypoxia-induced activation of AKT1 and AKT2, which mediate the repression of the viral oncogenes in hypoxic HPV-positive cancer cells." (PMID 30755508, 2019). "By extending the bridges of our sub-network with the literature survey results, we confirmed the oncosuppressor model of miR-148a through inhibition of cancer stemness by targeting SMAD2 in HCSC, AKT2 and KLF4." (PMID 30944375, 2019). "During investigations of the AKT signaling more and more evidence raised that the three isoforms AKT1 (PKBα), AKT2 (PKBβ) and AKT3 (PKBγ) exert distinct and partly even opposing effects in cancer and physiologically." (PMID 31752925, 2019). "Targeting the EMT signaling axis via AKT2/TWIST and PI3K/AKT2/mTOR in order to revert EMT and restore the epithelial phenotype appears to be a promising strategy in cancer therapy." (PMID 31357505, 2019). "AKT2, a member of the AKT kinase family, is frequently upregulated in various cancers, including CRC, where it contributes to the EMT process via the phosphatidylinositol 3′ kinase (PI3K)/AKT pathway." (PMID 28030836, 2017). "Akt2 is a potent regulator of the glucose transporter 1 (GLUT1), which facilitates uptake of glucose for cellular metabolism and is overexpressed in most cancer cells." (PMID 27533079, 2016). "Among the three highly homologous AKT isoforms(AKT1, AKT2, and AKT3), most studies have focused on the role of AKT1 in cancer progression." (PMID 26512921, 2015). "Four of these genes, AKT2, AKT3, G6PC, and GYS1, were particularly interesting because their involvement in the regulation of glycolysis in cancer has been well documented." (PMID 26512921, 2015). "Most of the genes, that are involved in many of the significantly enriched pathways, also play a role in pathways in cancer such as PTEN, JUN, AKT2, HSP90AA1, the latter of which was already described to influence radiosensitivity and chemosensitivity." (PMID 26328888, 2015). "There are three AKT isoforms (AKT1, AKT2, and AKT3) with different expression patterns and functions in several cancer tumors." (PMID 24338765, 2014). "Gain of 19q would result in increased copy number of several well known genes with involvement in cancer, such as BAX, CEACAM1, AKT2 and BCL2L12." (PMID 24144331, 2013). "We recently showed that BRCA1-IRIS overexpression promotes expression of AKT1, AKT2, p-AKT and survivin in human ovarian normal and cancer cell lines." (PMID 22511931, 2012). "All three isoforms of AKT, that is AKT1, AKT2, and AKT3, have been reported to be altered in various human cancers." (PMID 22666248, 2012). "AKT2 and HIF-1α activate transcription of a plethora of genes involved in cancer cells proliferation, survival, and progression." (PMID 22511931, 2012). "Known cancer genes included focal amplifications of MYC (8q24.21), KRAS (12p12.1) and AKT2 (19q13.2), and homozygous deletions of TGFBR2 (3p24.1) and CDKN2A (9p21.3)." (PMID 18535672, 2008). "It is noteworthy that many genes within these pathways (e.g., AKT2, AKT3, CREBBP, MAPK1, GNAS, RPTOR) are already known to play relevant roles in cancer cell growth and proliferation, which could provide a plausible biological basis for such a link." (PMID 41226303, 2025). "Interestingly, we discovered that the stable expression of EGFP-K-Ras(V12) resulted in reduced PI3-K p85α as well as Akt1 and Akt2 expression, but increased Akt3 expression in PANC-1 as well as Colo-699 cancer cells." (PMID 38291468, 2024). "Previous studies also indicated that, unlike Akt1 and Akt2 phosphorylation, Akt3 phosphorylation inhibits cancer cell proliferation." (PMID 38499532, 2024). "The overexpression of both Akt2 and HIF-1α is related to cancer progression, besides metabolism." (PMID 38139010, 2023).
cancer (continued). "Survival meta-analysis showed that NUAK1, Akt isoforms (Akt1, Akt2, and Akt3), mTOR, and Rictor positively correlate with a high hazard ratio (HR) in BRCA, COAD, GBM, PRAD, STAD, and OV, the same types of cancer where NUAK1 correlates with EGFR expression and Akt Ser-473 phosphorylation." (PMID 38135881, 2023). "Furthermore, luminal epithelial proliferation can be seen in highly metastatic cancers, making CD44v6 more specific for predicting ALNM than AKT2." (PMID 36532641, 2022). "Genetic alterations of the PIK3CA, mTOR, PTEN, AKT1, AKT2, and AKT3 genes in human cancers." (PMID 35402264, 2022). "Several kinds of AKT1-, AKT2-, and AKT3-regulating circRNAs are overexpressed in many cancer cells." (PMID 36230902, 2022). "Since HER-2 is not expressed in TNBC diagnosis, the production of nanobodies for the diagnosis and treatment of cancer cells should be performed against other antigens expressed in TNBC such as TNF-α, EGFR, CD3, CTLA-4, STAT3, AKT2, GTP-binding protein Rho, CapG, fibronectin, and CA-IX." (PMID 35933373, 2022). "In addition, junction analysis showed that abnormal expression of CPSF1 is related to ASEs of cancer-related genes, such as LAMC2, UBE2C, AKT2, AKT2, BOK, MAP4 and FANCD2." (PMID 34899345, 2021). "The activation of cancer-activated fibroblasts (CAF), which facilitates invasion of epithelial cells, required Akt2 which was activated by Snail and was distributed in polarized cells that were more abundant in the area of invasion in human breast tumor tissues." (PMID 34298660, 2021). "Even though AKT2 has previously been identified as a promising target for cancer treatment, its role in determining CSC phenotype has not been addressed." (PMID 31357505, 2019). "AKT2 is a well-known target for cancer treatment, and we have demonstrated its importance for CSC growth and dynamism in breast cell lines, suggesting that AKT2 could be an ideal candidate for an effective anti-cancer therapy." (PMID 31357505, 2019). "AKT2, BCL2, EWSR1 retrogene and MYCN for their cancer notoriety)." (PMID 30890123, 2019). "Combined, these results suggest that AKT1 and AKT2 may play opposite roles in the metastatic process and that differential AKT isoform activities require further consideration in cancer studies." (PMID 29506489, 2018). "Different cancer lineages displayed differential AKT1 and AKT2 expression and phosphorylation." (PMID 30012111, 2018). "Isoform-specific Akt abnormalities have been reported in many cancer cells, such as the overexpression of Akt1 in thyroid and non-small cell lung cancers, Akt2 and Akt3 in malignant glioma, and Akt3 in melanoma, ovarian, and breast cancer." (PMID 28483982, 2017). "AKT2 was overexpressed in BC specimens, and its expression levels were much higher in ERα positive cancer tissues than those ERα negative cancer tissues." (PMID 27175587, 2016). "AKT2 is known to promote EMT progression, thereby inhibiting cancer growth and metastasis." (PMID 26158514, 2015). "In addition to known cancer driver genes such as ERBB2 (6% of cases), NRAS (3%), MET (3%), PIK3CA (1%), AKT2 (1%), TSC1 (1%), and ERBB4 (1%), several putative cancer genes were identified, such as PTPRC, SYNE2, GRIN2A, and CDH10." (PMID 24576404, 2014). "In 28 paired primary protein samples, AKT2 protein expression showed up-regulated in the cancer tissues compared with adjacent non-tumorous tissues after quantification (P = 0.001)." (PMID 25288334, 2014). "Further studies focusing on Akt2 signaling in CD8+ T-cell differentiation could uncover additional mechanisms that enhance T-cell persistence, memory potential, and antitumor efficacy, thereby broadening its therapeutic applicability in cancer immunotherapy." (PMID 40139836, 2025).
cancer (continued). "Notably, of the eight cancer-related genes, six (TSC1, TSC2, PIK3CA, IGF1R, PDPK1 and AKT2) are known longevity related genes according to GenAge database in human/model organisms, and genetic manipulation of these genes can directly lead to shortening or extending lifespan of model organisms." (PMID 37582720, 2023). "For instance, AKT1, AKT2, and AKT3, belonging to the five pathways of signaling by GPCR, GPCR downstream signaling, innate immune system, adaptive immune system, and developmental biology, are three isoforms of AKT in PI3K/AKT pathway, which is an important drug target in many cancers including GBM." (PMID 30558539, 2018). "Additionally, derivative 6 induced growth inhibition on different cancer cell lines in the low micromolar range (4.5, 5.7, and 8.7 μM in PC3, HCT116, and U87MG cell lines, respectively) and decreased the levels of pGSK3, pS6, and pFKHR proteins, that are downstream targets of the AKT2 pathway." (PMID 37513905, 2023). "Collectively, our results have shown the involvement of AKT2, but not AKT1 and AKT3, in cancer cell migration and invasion thereby acquiring the characteristics of cancer stem cell." (PMID 33227065, 2020). "Lastly, they found that Akt1 and Akt3, but not Akt2, interact with DNA-PKcs in K-Ras mutant cells and stimulate DSB repair, thereby protecting cancer cell against IR." (PMID 33266502, 2020). "To confirm the central role of AKT2, we silenced AKT2 expression via small interfering RNA and using a chemical inhibitor (CCT128930), in both CSC and non-CSC from different cancer cell lines." (PMID 31357505, 2019). "AKT comprises three isoforms (AKT1, AKT2, and AKT3), and the different isoforms are believed to mediate critical non-redundant or even opposing functions in cancer pathophysiology." (PMID 30012111, 2018). "This is consistent with findings that AKT2 does not share complementary functions with AKT1 regarding cell invasiveness and survival in other forms of cancer." (PMID 20409325, 2010). "Unlike AKT2, amplification of AKT1 is a rare occurrence in human cancer." (PMID 39614261, 2024). "Moreover, here we showed the involvement of AKT2, but not of AKT1, in the remodeling of the actin cytoskeleton, which is also relevant to cancer cell migration." (PMID 28287129, 2017).
infection (17 papers, 2010 to 2024). The state of being infected such as from the introduction of a foreign agent such as serum, vaccine, antigenic substance or organism. "In addition, cells deficient in AKT1 or AKT2 were more resistant to LGTV-induced cell death due to higher amounts of pAKT at a late stage in infection." (PMID 32977414, 2020). "Surface electrocardiograms (ECG) were measured in 6-week-old WT (n = 4) and AKT2 KO (n = 3) mice at 3 days post-infection." (PMID 35163412, 2022). "Infiltration of the inflammatory cells increased significantly in AKT2 KO mouse hearts on Day 14 post-infection compared with WT mice." (PMID 35163412, 2022). "At an early stage (3–5 days post-infection), mortality dramatically increased in AKT2 KO mice compared with WT mice (72.9% vs. 26.7%)." (PMID 35163412, 2022). "In this study, we extended our previous work identifying increased AKT2 mRNA by investigating the role played by AKT isoforms during the acute phase of infection up through the lytic crisis." (PMID 32977414, 2020). "We found that AKT1 and AKT2 were downregulated at the protein level during the acute phase of infection, but AKT3 was upregulated." (PMID 32977414, 2020). "Surprisingly, we found that AKT1 KO and AKT2 KO cells survived the acute phase of infection in greater numbers compared to the WT cells." (PMID 32977414, 2020). "We observed that AKT1 and AKT2 levels decrease over time as infection progressed, but AKT3 was dramatically increased at 120 hpi." (PMID 32977414, 2020). "Then, we overexpressed AKT2 in two CRC cells by lentivirus infection, finding out that ectopic expression of AKT2 in miR-612-overexpressing CRC cells rescued cell growth and migration activity." (PMID 26158514, 2015). "Compared with the infection model group, the mitochondrial autophagy inhibitor group exhibited significantly decreased levels of p-AKT2 and p-mTOR, whereas the levels of these proteins were significantly increased in the mitochondrial autophagy inducer group (P < 0.05)." (PMID 37077346, 2023). "mTOR expression in the AKT2 inhibitor group and the mitochondrial autophagy inhibitor group was 0.761 ± 0.213 and 0.803 ± 0.286, respectively, and showed significant differences compared with the infection model group (P < 0.05)." (PMID 37077346, 2023). "mTOR expression in the mitochondrial autophagy inducer group was 1.360 ± 0.479, which was comparable to that in the control group and infection model group (P > 0.05) but was significantly higher than that in the AKT2 inhibitor group and mitochondrial autophagy inhibitor group (P < 0.05)." (PMID 37077346, 2023). "Compared with the infection model group, the mitochondrial autophagy inhibitor group exhibited significantly lower levels of p-AKT2 and p-mTOR, whereas the mitochondrial autophagy inducer group exhibited significantly higher levels of these proteins (P < 0.05)." (PMID 37077346, 2023). "We also discovered that cells individually lacking AKT1 or AKT2 survive LGTV infection better than WT cells, and this was associated with higher amounts of antiapoptotic XIAP and survivin and increased resistance to LGTV-induced apoptotic cell death." (PMID 32977414, 2020). "AKT1 and AKT2 levels decreased as infection progressed, compared to the mock infected cells." (PMID 32977414, 2020). "Total cell lysates prepared from mouse lungs at 12, 20 and 32 weeks post-infection with AJEJJenv were probed by western blot with antibodies against Akt1, Akt2 and Akt3 to determine whether Akt isoform expression levels varied relative to normal lung." (PMID 24722238, 2014). "In contrast, Akt2 disruption was related to a reduction of total Akt pT308 both in 1 DIV infection (62.29%±8.80 respect to the control; p<0.01, n=3) and 6 DIV infection conditions (52.41%+7.20 respect to the control; p<0.01, n=3), although no significant changes were observed in total Akt pS473." (PMID 22509246, 2012).